Y_RNA (Y RNA )
Gene: Miscellaneous RNA gene on chromosome 20 (50,563,009 to 50,563,110, forward strand). Ensembl gene ENSG00000201501.
Homologues: Orthologues: chimpanzee Y_RNA (100% identical), macaque Y_RNA (99% identical), pig Y_RNA (75% identical). Paralogues in human: Y_RNA (90% identical), Y_RNA (89% identical), RNY3 (88% identical), Y_RNA (88% identical), Y_RNA (87% identical), Y_RNA (86% identical), RNY3P1 (85% identical), RNY3P13 (85% identical), RNY3P14 (85% identical), Y_RNA (85% identical), RNY3P16 (84% identical), Y_RNA (84% identical), and 97 more.